CDKN2A (cyclin dependent kinase inhibitor 2A)
Diseases named in the same sentence as CDKN2A in open-access papers (continued):
Sharing a sentence is not in itself a finding about the gene and the disease.
sarcomatoid mesothelioma (6 papers, 2018 to 2025). A diffuse malignant mesothelioma arising from the pleura and less often the peritoneum. "In more than 90% of cases, sarcomatoid mesothelioma is found to have a CDKN2A homozygous deletion or loss of methylthioadenosine phosphorylase gene (MTAP), and in most cases, co-deletion is seen." (PMID 39409190, 2024). "Importantly, CDKN2A mutations exhibit a strong association with poor prognosis, particularly prevalent in sarcomatoid mesothelioma." (PMID 40904706, 2025). "In the same way, immunohistochemistry for MTAP or homozygous deletion of 9p21 (CDKN2A) in FISH is useful mainly in sarcomatoid mesothelioma that exhibit these losses in >80% of cases." (PMID 35204459, 2022).
anaplastic oligodendroglioma (5 papers, 2004 to 2024). A WHO grade III oligodendroglioma with focal or diffuse malignant morphologic features (prominent nuclear pleomorphism, mitoses, and increased cellularity). "With regard to target genes, the CDKN2A tumour suppressor gene located on 9p21 is found to be homozygously deleted in about 25% of anaplastic oligodendrogliomas and the PTEN gene maps to 10q23 is mutated in 8% of anaplastic oligodendrogliomas." (PMID 15475940, 2004).
bone tumors (5 papers, 2010 to 2024). "In this study, it was found that about 34% of Chinese bone tumor patients harbored actionable targeted mutations, including CDKN2A, PTEN, FGFR1/2/3, NF1, and NTRK1/2/3." (PMID 35756627, 2022). "Consistent with WES and RNA expression data, we observed no CDKN2A protein expression in the PDX-Bone tumor." (PMID 30236142, 2018).
cognitive decline (5 papers, 2016 to 2025). "Of these, 3 (TAU3, GFAPα, and CDKN2A (p14ARF)) were associated with mild cognitive decline in ageing humans." (PMID 31654269, 2019). "Collectively, these findings led us to conclude that NFTs were directly linked to senescence‐associated Cdkn2a upregulation, which in turn was a strong predictor of neurodegeneration and cognitive decline." (PMID 30126037, 2018). "The cyclin-dependent kinase inhibitor p16INK4a (encoded by CDKN2A), a key regulator of cellular senescence, has been identified as a highly specific biomarker of aging-related cognitive decline in both animal models and human postmortem studies." (PMID 41429887, 2025). "The associations between GFAPΑ and CDKN2A (p14ARF) were not apparent in severe cognitive decline, although this may reflect low power imposed by the inherent variability of human biological samples, since p14 expression in severe decline is trending in the same direction." (PMID 31654269, 2019). "Finally, associations were identified between peripheral blood GFAPα, TAU3, and CDKN2A (P14ARF) isoform levels and mild or severe cognitive decline over a 3–7-year period." (PMID 31654269, 2019).
esophageal tumors (5 papers, 2010 to 2025). "CDKN2A gene exon 2 was also found to be methylated in esophageal tumors." (PMID 33896386, 2021). "In a second esophageal tumor sample, SA528899, an L1 element integrated into chromosome 9 promoted an 8.6-Mb clonal deletion that encompasses the 9p22.1–9p21.1 region that removes one copy of the same tumor-suppressor gene, CDKN2A." (PMID 32024998, 2020).
hereditary cancer (5 papers, 2016 to 2026). Malignant neoplasms occurring in families at a rate greater than that expected by chance and caused by germline mutations in a specific gene. "The CDKN2A (c.146T>C) variant has been found in hereditary cancer patients within the Mexican population." (PMID 42194989, 2026). "A complete loss of a gene, as described in the MGI database, as well as pathogenic mutations, which in the case of CDKN2A can lead to hereditary cancer in human, are expected to display much stronger effects than regulatory influences such as those exerted by hsa-miR-4513." (PMID 34605899, 2022). "The observed variant belongs to non-conserved region of CDKN2A, yet it has been cataloged in ClinVar associated with hereditary cancer-predisposing syndrome with uncertain significance." (PMID 32655615, 2020).
HIV-1 infection (5 papers, 2010 to 2025). The type species of lentivirus and the etiologic agent of acquired immunodeficiency syndrome (AIDS). "Three of these genes baculoviral IAP repeat containing 2 (Birc2), Myc and FN1 are strongly down-regulated, and CDKN2A, CDKN2B and BRAC1 are moderately down-regulated during acute HIV-1 infection." (PMID 21533265, 2011).
hypopharyngeal carcinoma (5 papers, 2017 to 2024). Carcinoma, predominantly squamous cell, arising from the epithelial cells of the hypopharynx. "In this study, CDKN2A was found down-regulated expression (61.0%) and point mutation (4.5%), suggesting CDKN2A and CDKN2B deficiency and inactivation may contribute to hypopharyngeal carcinoma progression." (PMID 29156722, 2017). "Moreover, we identified several copy number variants (CNVs) genes were associated with hypopharyngeal carcinoma, one with amplification (ATF1) and two with deletions (CDKN2A, CDKN2B)." (PMID 29156722, 2017). "A significant association of point mutations in CCND1 and CDKN2A, as well as chromosomal instability based on copy number variation, was associated with progression-free survival in oropharyngeal and hypopharyngeal carcinoma independent of HPV status according to mutation analyses of 556 genes." (PMID 33801877, 2021).
leukoplakia (5 papers, 2014 to 2025). A white patch or plaque on a mucous membrane that cannot be characterized clinically or pathologically as any other disease.
lichen sclerosus (5 papers, 2010 to 2021). "We also confirmed that CDKN2A plays a critical role in tumorigenesis of PSCC, which has been reported to be preferentially occurred in lichen sclerosus-external genital carcinoma." (PMID 34150614, 2021).
mucinous ovarian tumors (5 papers, 2014 to 2025). "Benign mucinous ovarian tumors frequently harbor mutations in KRAS or Cyclin-dependent kinase inhibitor 2A (CDKN2A)." (PMID 39040449, 2024). "From these reports, it appears that loss of Cdkn2a in mucinous ovarian tumors with V600E BRAF mutation impairs progression to carcinoma." (PMID 32556513, 2020). "Furthermore, it has recently been shown that pre-invasive ovarian mucinous tumors are characterized by cyclin-dependent kinase inhibitor 2A (CDKN2A) and Ras pathway aberrations." (PMID 24936796, 2014).
mucinous tumors (5 papers, 2015 to 2023). "Nonetheless, we and others have shown that mucinous tumors have a high proportion of mutations in RAS pathway genes and aberration of CDKN2A (p16)." (PMID 26257827, 2015). "Another report generated the relationship between benign, borderline, invasive low-grade and high-grade mucinous tumors and found that either a KRAS or CDKN2A event leads to the initiation of benign tumors." (PMID 37185420, 2023). "A minority of mucinous tumors does not display KRAS or BRAF oncogenic mutations; in these tumors, alternative mechanisms drive constitutive RAS signaling, such as RRAS2 mutation, HER2 amplification, ARID1A truncating mutation or ELF3 mutation plus homozygous CDKN2A loss." (PMID 29389895, 2018).
Pancreatic cysts (5 papers, 2019 to 2025). A cyst of the pancreas that possess a lining of mucous epithelium. "Along this line, a recent molecular investigation on pancreatic cyst fluid already described CDKN2A alterations as a marker of advanced pancreatic neoplasia." (PMID 40371932, 2025). "Six of the 27 mutation carriers (22%) had pancreatic cysts of unknown type detected, including 1 ATM carrier, 3 BRCA2 carriers, and 2 CDKN2A carriers." (PMID 32601617, 2019).
Parkinson disease (5 papers, 2020 to 2026). A progressive degenerative disorder of the central nervous system characterized by loss of dopamine producing neurons in the substantia nigra and the presence of Lewy bodies in the substantia nigra and locus coeruleus. "In Parkinson’s disease patients, SATB1 (a CDKN1A inhibitor) levels are reduced in the substantia nigra, while CDKN2A, MMP3, IL-6, IL-1α, and CXCL8 levels are elevated, indicating an increased aging burden." (PMID 39963130, 2025).
pituitary adenomas (5 papers, 2012 to 2025). "CDK inhibitors CDKN1B (p27), CDKN2A (p16), and CDKN2C (p18) are involved in G1-S transition, provide growth inhibitory signals and exhibit alterations in pituitary adenomas." (PMID 23226476, 2012).
Richter syndrome (5 papers, 2016 to 2022). Transformation of chronic lymphocytic leukemia into aggressive non-Hodgkin's lymphoma, usually diffuse large B-cell lymphoma (immunoblastic or centroblastic variant). "A quite similar pattern is observed in the transformation from CLL to DLBCL (Richter syndrome) with the deletion at the CDKN2A/B locus as the most common acquired event." (PMID 33344238, 2020).
testicular germ cell tumor (5 papers, 2010 to 2023). A germ cell tumor arising from the testis. "CDKN2A was significantly upregulated in 32 tumor types, while its expression was significantly decreased in TGCTs (Testicular Germ Cell Tumors) (tumor: 1.59 ± 1.22, normal: 4.30 ± 1.19, p = 3.7e-39)." (PMID 37950153, 2023). "For example, CDKN2A was highly upregulated for almost all cancer types but apparently suppressed in testicular germ cell tumors (TGCT) (log2FC = −2.74)." (PMID 35911954, 2022). "However, the immune scores of BRCA, CESC, KIRC, LGG (Brain Lower Grade Glioma), OV (Ovarian serous cystadenocarcinoma), READ, TGCT (Testicular Germ Cell Tumors), and THCA and the stromal scores of COAD, TGCT and THCA were negatively correlated with the CDKN2A expression level." (PMID 35004697, 2021).
thymic epithelial tumors (5 papers, 2013 to 2024). "Together, these data arguably make CDKN2A/p16 one of the most relevant altered genes in thymic epithelial tumors." (PMID 38473304, 2024).
xeroderma pigmentosum (5 papers, 2004 to 2024). Xeroderma pigmentosum (XP) is a rare genodermatosis characterized by extreme sensitivity to ultraviolet (UV)-induced changes in the skin and eyes, and multiple skin cancers. "For instance, heritable mutations such as in MC1R, CDK4, and CDKN2A, as well as genetic conditions like xeroderma pigmentosum (XP), have all been associated with an increased risk of melanoma development." (PMID 38067178, 2023).
actinic keratosis (4 papers, 2017 to 2025). A precancerous lesion of the skin composed of atypical keratinocytes. "Furthermore, cSCC often has heterozygous deletions or point mutations in the CDKN2A gene locus, and the deletion of p16INK4a is thought to be related to the progression of actinic keratosis (AK) to cSCC." (PMID 36247089, 2022). "Alterations of CDKN2A have been reported in 10-30 percent of SCC and in a limited number of actinic keratosis." (PMID 28410231, 2017).
acute leukemia (4 papers, 2016 to 2021). A clonal (malignant) hematopoietic disorder with an acute onset, affecting the bone marrow and the peripheral blood. "In acute leukemias, homozygous deletion of CDKN2B and CDKN2A occurs in approximately 30% of ALL patients." (PMID 30635552, 2019). "Mice transplanted with CDKN2A-/-/NRAS Q61K/EZH2Δ/Δ mutated lineage-negative, SCA-positive, and c-Kit-positive (LSK) cells generate acute leukemia with the ETP-ALL phenotype." (PMID 34912707, 2021).
ameloblastoma (4 papers, 2014 to 2022). The most common odontogenic tumor, arising from the epithelial component of the embryonic tooth and usually affecting the molar-ramus region of the mandible or maxilla. "In genome analysis, the CpG methylation of p16 (cyclin-dependent kinase inhibitor 2A) is observed in all ameloblastic carcinoma samples, but only one ameloblastoma specimen exhibits the mutation." (PMID 24799899, 2014). "It is notable that the presence of two or three gene mutations, including somatic mutations in KRAS, PIK3CA, PTEN, FGFR, CDKN2A, and CTNNB1 in the background of either BRAF or SMO mutation-positive ameloblastomas, exclusively occurred in solid/conventional tumors." (PMID 35048058, 2021). "Aside from the SMO mutations, APC mutations have been detected in 3/6 ameloblastomas, and CTNNB1, PIK3CA, SMARCB1, PTEN, CDKN2A mutations have been reported in a few cases and tend to occur in a non-mutually exclusive manner with BRAF p.V600E mutation and with each other." (PMID 35048058, 2021). "However, somatic KRAS, PIK3CA, PTEN, FGFR, CDKN2A, and CTNNB1 co-occurred also in the background of either BRAF- or SMO-mutated ameloblastomas." (PMID 29388014, 2018).
carcinoid (4 papers, 2015 to 2025). "ASCL1 (p = 0.0016), BCL2 (p < 0.0001), CASP8 (p = 0.0030), CCNE1 (p = 0.0135), CDK1 (p = 0.0146), CDK2 (p = 0.0114), CDKN1A (p = 0.0107) and CDKN2A (p = 0.0002) showed lower expression in carcinoids compared to carcinomas." (PMID 26008974, 2015). "Additionally, CDKN2A, the regulatory inhibitor of CDK4/6, shows minimal to no expression in carcinoids." (PMID 26008974, 2015).
chronic cervicitis (4 papers, 2015 to 2024). Chronic inflammation of the cervix. "We used a set of patient-derived precancerous (n = 32) and noncancerous (chronic cervicitis; n = 10) tissue samples to investigate the gene expression of several OIS (LMNB1, CDKN2A, CDKN2B, and CDKN1A), and SASP (IL1A, CCL2, TGFB1, CXCL8, and MMP9) biomarkers using qRT-PCR." (PMID 39727946, 2024).
chronic myeloid leukemia (4 papers, 2014 to 2023). "KEGG analysis in the BaF3-T315 cells showed that the chronic myeloid leukemia signaling pathway (genes such as Cdk4, Tgfbr1, Gadd45b, Mdm2, Gadd45g, Polk, Rb1, Ctbp1, and Cdkn2a were enriched) was involved in the I13 treatment." (PMID 37124196, 2023).
co-infection (4 papers, 2020 to 2023).
colon adenocarcinoma (4 papers, 2024 to 2025). "Furthermore, survival analyses based on gene expression (TCGA & GTEx profile) and mutational status (TCGA COAD & Pan‐cancer datasets) for colon adenocarcinoma identified CDKN2A, INHBA increased expression, and CDKN2A and TCF7L2 mutations as predictors of bad prognosis in metastatic patients." (PMID 40658092, 2025). "However, this study aims to investigate the role of CDKN2A as a diagnostic and prognostic biomarker across various types of cancer focusing primarily on colon adenocarcinoma (COAD)." (PMID 38894777, 2024).
cyst (4 papers, 2017 to 2022). A sac-like closed membranous structure that may be empty or contain fluid or amorphous material. "While CDKN1B and CDKN1C expression was higher in normal subtypes, senescence-related CDK inhibitors CDKN1A and CDKN2A were more abundant in PKD-CDC subtypes, suggesting that cyst-lining cells may be prone to cellular senescence due to cellular stress." (PMID 36310237, 2022).
endometrioid carcinomas (4 papers, 2014 to 2025).
endothelial dysfunction (4 papers, 2019 to 2026). In vascular diseases, endothelial dysfunction is a systemic pathological state of the endothelium (the inner lining of blood vessels) and can be broadly defined as an imbalance between vasodilating and vasoconstricting substances produced by (or acting on) the endothelium. "Then, NOTCH1, PPARG, NOS3, KEAP1, CDKN2A, and IRS1 were predicted to affect endothelial dysfunction of ED as autophagy-related hub genes." (PMID 34447638, 2021). "NOTCH1, CDKN2A, and NOS3 are involved in the regulation of endothelial dysfunction and may be potential therapeutic targets for ED by modulating autophagy." (PMID 34447638, 2021).
Fanconi anemia (4 papers, 2019 to 2025). Fanconi anemia (FA) is a hereditary DNA repair disorder characterized by progressive pancytopenia with bone marrow failure, variable congenital malformations and predisposition to develop hematological or solid tumors. "Other defects in homologous recombination repair genes, such as EMSY, RAD51, ATM, ATR, Fanconi anemia, BARD1, BRIP1, PALB2, RB1, NF1, CDKN2A, and the suppression of BRCA1 transcriptional activation through gene methylation, are associated with homologous recombination deficiency (HRD)." (PMID 32679669, 2020).
gallbladder cancer (4 papers, 2021 to 2024). "Recent reports have emphasized the importance of promoter methylation in specific genes, including CDH1, CDKN2A-p16, REPRIMO (a tumor suppressor gene family), and UCHL1 (also known as PGP9.5) in the development of gallbladder cancer." (PMID 38786750, 2024).
Hodgkins lymphoma (4 papers, 2008 to 2022). A heterogeneous group of malignant lymphoid neoplasms of B-cell origin characterized histologically by the presence of Hodgkin and Reed-Sternberg (HRS) cells in the vast majority of cases. "Module II consists of miRNAs from the Hodgkin Lymphoma cell line, hsa-miR-17, hsa-miR-24, and ebv-miR-BART3, and genes from the "regulation of lymphocyte activation" category - CDKN2A and ICOSLG." (PMID 20465802, 2010).